FAM162B (family with sequence similarity 162 member B)
Synonyms: C6orf189; bA86F4.2
Tractability: Antibody: UniProt predicts a signal peptide or a membrane-spanning region.
Gene: Protein-coding gene on chromosome 6 (116,751,703 to 116,765,719, reverse strand). Ensembl gene ENSG00000183807.
Subcellular location: Membrane
Gene Ontology:
Cellular component: membrane
Genetic constraint (gnomAD): Loss-of-function variants: 12 observed, 11.38 expected, observed/expected ratio (o/e) 1.05, 90% interval 0.67 to 1.67. The upper end of that interval is the gene's LOEUF score, 1.67, which puts it in group 6 of 6, group 1 being the genes least tolerant of losing a copy. Missense variants: 222 observed, 152.45 expected, observed/expected ratio (o/e) 1.46, 90% interval 1.3 to 1.63. Synonymous variants: 63 observed, 56.86 expected, observed/expected ratio (o/e) 1.11, 90% interval 0.9 to 1.37.
Homologues: Orthologues: chimpanzee FAM162B (100% identical), macaque FAM162B (95% identical), rabbit FAM162B (82% identical), pig FAM162B (81% identical), dog FAM162B (76% identical), mouse Fam162b (66% identical), guinea pig FAM162B (58% identical), tropical clawed frog fam162b (47% identical), zebrafish fam162a (41% identical), Drosophila melanogaster CG9231 (25% identical), Caenorhabditis elegans taap-1 (15% identical). Paralogues in human: FAM162A (38% identical).
Diseases named in the same sentence as FAM162B in open-access papers:
FAM162B is named in the same sentence as 5 diseases in open-access papers, as found by Europe PMC text mining. Sharing a sentence is not in itself a finding about the gene and the disease. The quoted sentences say what the papers report.
Hirschsprung disease (1 paper, 2015). Hirschsprung disease (HSCR) is a congenital intestinal motility disorder that is characterized by signs of intestinal obstruction due to the presence of an aganglionic segment of variable extent in the terminal part of the colon. "In conclusion, this study not only allowed the identification of Fam162b coding and regulatory sequences as novel candidate loci for Hirschsprung’s disease but also provides important new insights into its male sex bias." (PMID 25786024, 2015).
tumor (1 paper, 2016). "Also sex and tumor stage did not influence read-through transcript levels, except for FAM162B–ZUFSP which had a significant association with both covariates and for NFATC3–PLA2G15 whose levels were associated with sex." (PMID 27058892, 2016).
FAM162B also shares sentences with these, for which no sentence is quoted: colon disease (1 paper); deafness (1); Waardenburg syndrome (1).